IL6 (interleukin 6)
Diseases named in the same sentence as IL6 in open-access papers (continued):
Sharing a sentence is not in itself a finding about the gene and the disease.
schizophrenia (continued). "Indeed, recent studies have shown that prenatal exposure to proinflammatory agents like Il–6, Il–8, and TNF alpha can increase the risk for diseases like autism or schizophrenia by inducing both neuromorphological and neurochemical changes in the immature brain." (PMID 24381719, 2013). "Furthermore, in a recent meta-analysis in which the effect of 10 cytokines plasma levels in schizophrenia was assessed, including IL-10, only significant trends have been observed for IL-1RA, sIL-2R and IL-6, providing evidence of an inflammatory syndrome in schizophrenia." (PMID 21658228, 2011). "We previously identified IL-6, IL-8, IL-1β, and SERPINA3 mRNAs as the most upregulated inflammation markers in the PFC of schizophrenia cases, whereas the most discriminatory markers in the midbrain also included TNF mRNA." (PMID 41567988, 2026). "Altered expression of several miRNAs, including those modulating IL-6 and tumor necrosis factor alpha (TNF-α) signaling, has been reported in recent-onset schizophrenia." (PMID 41302331, 2025). "PANSS scores in schizophrenia patients correlated with IL-6 and TNF-α serum levels, whereas MDD patients showed correlations between IL-6 and IL-1β levels and HAM-D scores." (PMID 40416228, 2025). "By using the Western blot technique, we found notably high concentrations of the inflammatory mediators IL1β, IL-6, and TNF-α in the serum of patients with schizophrenia compared with in the controls." (PMID 41011185, 2025). "Research indicated that schizophrenia and MDD patients had higher levels of IL-6, TNF-α, and IL-1β as compared to healthy controls." (PMID 40416228, 2025). "For instance, 6-week treatment with olanzapine reduced proinflammatory cytokines such as IL-1 β, IFN-γ, IL-6 and TNF-α levels, in schizophrenia patients and increased the proinflammatory cytokines such as IL-10." (PMID 39907868, 2025). "Elevated concentrations of cytokines such as interleukin-6 (IL-6), tumor necrosis factor-alpha (TNF-α), and interleukin-1 beta (IL-1β) have been repeatedly observed in individuals with schizophrenia." (PMID 40635756, 2025). "This study demonstrated that schizophrenia and MDD were inflammatory disorders because enhanced IL-6, TNF-α, and IL-1β levels showed direct links to symptom intensity in affected patients." (PMID 40416228, 2025). "High serum levels of interleukin 1β (IL-1β), IL-6, or tumor necrosis factor-α (TNF-α), often manifested during acute relapse of schizophrenia, are significantly reduced by antipsychotic therapy." (PMID 41010622, 2025). "Age, smoking habit, BMI and IL-6 levels, medication time, elevated CRP levels, and exercise habit were the influencing factors for the development of MS in schizophrenia." (PMID 41450839, 2025). "We reported a reduction in IL-6 and IL-12 induced by ECT with concomitant amelioration of schizophrenia symptoms." (PMID 40364201, 2025). "On the other hand, pro-inflammatory cytokines produced during maternal viral infection, particularly IL-6, are known to modulate neurodevelopmental processes, including cell proliferation, neurite extension, and synaptic protein expression, factors that may be aberrant in schizophrenia." (PMID 40806558, 2025). "Patients with schizophrenia and first episode psychosis (FEP) display abnormal profiles of proinflammatory cytokines (especially IL-6 and TNF-α) prior to start of treatment." (PMID 38177535, 2024). "It has been suggested that both IL-6 and TGF-β1 are indicators of acute exacerbations of schizophrenia, so their levels are potentially increased during acute states in comparison to the control group." (PMID 39595201, 2024). "Evidence-based studies are representative of altered levels of inflammatory cytokines, including C-reactive protein, IL-1, IL-6, and TNF-α in schizophrenia patients, which affect the basal ganglia and induce negative symptoms." (PMID 39716387, 2024).
schizophrenia (continued). "The main objective of this study was to assess the effects of ECT on cytokines such as IL-6, IL-12, IL-5, IL-10 and TGF-β1 in patients with treatment-resistant schizophrenia." (PMID 39595201, 2024). "Regarding inflammatory factors, a meta-analysis reported elevated levels of IL-6, IL-1β, and TNF-α in the blood and cerebrospinal fluid of individuals with schizophrenia." (PMID 39324122, 2024). "NCE considerably decreases the malondialdehyde (MDA) and DA levels and IL-6 and TNF-α expressions in mice with schizophrenia-like symptoms." (PMID 38371525, 2024). "We found that pro-inflammatory cytokines IL-6, TNF-α and IFN-γ had the greatest influence (relative to other cytokines) in a network involving a large set of both pro- and anti-cytokines in schizophrenia." (PMID 37723153, 2023). "We report that IL-6, TNF-α and IFN-γ had the greatest influence in a network of cytokines in individuals with schizophrenia." (PMID 37723153, 2023). "Abnormal levels of inflammatory factors including C-reactive protein, transforming growth factor α(TGF- α), interleukin-6 (IL-6) and insulin-like growth factor (IGF-I) in schizophrenia were confirmed in the observational and MR studies." (PMID 37743466, 2023). "The serum levels of Interleukin 1 beta (IL-1β), Interleukin 6 (IL-6), and transforming growth factor beta (TGF-β) were found to be elevated in acute phases of schizophrenia." (PMID 37803327, 2023). "For example, serum levels of interleukin-6 (IL-6) and tumor necrosis factor-α (TNF-α) are found to be raised in acute psychotic relapses in patients with schizophrenia." (PMID 37376644, 2023). "IL-1β, IL-2, IL-4, IL-6, BAFF, IFN-α, GM-CSF, NRG1-β1, and GDNF increased but TNF-α and NGF-β decreased in schizophrenia compared to healthy individuals." (PMID 37239308, 2023). "For example, blood and cerebrospinal fluid concentrations of pro-inflammatory cytokines, including interleukin (IL)-6, IL-8, interferon gamma (IFNγ), tumor necrosis factor alpha (TNF-α), and others, are increased in schizophrenia." (PMID 37239308, 2023). "It is recommended that miRNA levels assess by disease severity and clinical profiles to provide reliable evidence for the concoctions between higher levels of IL-6, IL-1β, TNF-α, and mi-RNAs in patients with schizophrenia in comparison with controls." (PMID 37644489, 2023). "For instance, interleukin-6 (IL-6), tumor necrosis factor-α (TNF-α), and oxidative stress have been found in high levels in both keratoconus and schizophrenia patients." (PMID 37602110, 2023). "Compared with healthy people, IL-6 and TNF-α levels were significantly increased in schizophrenia patients, while IL-2, IL-4 and IFN-γ levels were significantly decreased." (PMID 37582716, 2023). "On the contrary, decreased cognitive performance in patients with schizophrenia was observed with higher TLR2 activity (whole blood-stimulated) and elevated IL-6 plasma." (PMID 37627253, 2023). "To explore this, we measured suPAR, CRP, TNF, sTNFR1 and IL-6 in plasma obtained before and after a 12-week exercise intervention RCT in individuals with schizophrenia." (PMID 37265560, 2023). "Cytokine levels including IL-2, IL-4, IL-6, IL-10, TNF-α, and IFN-γ were tested, and we found significantly higher levels of IL-6 in patients with schizophrenia (P < 0.01)." (PMID 38066312, 2023). "In this work, we found significantly higher serum levels of proinflammatory (IFN-γ, IL-5, IL-6, IL-8, IL-15, and TNF-α) and anti-inflammatory (TGF-α, IL-10, and IL-1RA) cytokines in patients with schizophrenia than in healthy individuals." (PMID 36556337, 2022). "A meta-analysis showed increased levels of IL-6, IL-8, IL-10, IL-12, IL-1β, IFN-γ, TNF-α, and TGF-β in the blood of patients with schizophrenia, which was similar to our findings." (PMID 35223927, 2022).
schizophrenia (continued). "We found higher TGF-α (p = 0.014), IFN-γ (p = 0.036), IL-5 (p < 0.001), IL-6 (p = 0.047), IL-8 (p = 0.005), IL-10 (p <0.001), IL-15 (p = 0.007), IL-1RA (p = 0.007), and TNF-α (p < 0.001) levels in patients with schizophrenia than in healthy individuals." (PMID 36556337, 2022). "We found higher TGF-α (p = 0.014), IFN-γ (p = 0.036), IL-5 (p < 0.001), IL-6 (p = 0.047), IL-8 (p = 0.005), IL-10 (p < 0.001), IL-15 (p = 0.007), IL-1RA (p = 0.007), and TNF-α (p < 0.001) levels in patients with schizophrenia compared with healthy individuals." (PMID 36556337, 2022). "Meta-analytical evidence shows elevated levels of IL-6 in the peripheral blood and cerebrospinal fluid (CSF) of individuals with FEP and diagnosis of schizophrenia." (PMID 35963926, 2022). "A previous study found evidence for a subgroup of patients with schizophrenia and bipolar disorder positive for the human endogenous retrovirus type W (HERV-W) envelope protein that exhibit increased levels of IL-6 and IL-1β." (PMID 36085284, 2022). "A considerable number of studies, including meta-analyses, have revealed elevated levels of IL-6 and TNF-α in various groups of patients with schizophrenia." (PMID 36556337, 2022). "We also investigated markers of inflammatory response (C-reactive protein, IL-2, IL-6, IL-10), the activity of leukocytic elastase (LE) and α1-proteinase inhibitor (a1-PI), antibodies to S100B and myelin basic protein (MBP) in schizophrenia." (PMID 34025476, 2021). "The significant positive correlation provides an indirect support to the association between childhood trauma and the up-regulation of both IL6 and FKBP5 in the patients with schizophrenia included in our meta-analysis." (PMID 33673722, 2021). "In the case of IL-1β, IL-6 and TNF-α, their potential roles as trait markers of schizophrenia seem to be supported by correlations with the results of neuroimaging studies,; and in the case of TNF-α and IL-6, also with the experience of early childhood trauma." (PMID 34501305, 2021). "Increase in the plasma levels of proinflammatory cytokines, such as IL-1β, IL-6, and TNF-α, have been consistently reported in patients with schizophrenia." (PMID 34393855, 2021). "An increased level of inflammatory cytokines, especially IL-6 and TNF-α, has also been found in the circulation of acutely ill patients with schizophrenia, bipolar disorder, and MDD." (PMID 34650454, 2021). "Increased levels of IL-6, IFN-γ, TNF-α, and TGF-β were also noted in acute relapsed schizophrenia inpatients (AR)." (PMID 34199832, 2021). "The correlation table showed the relationships between the Kyn pathway metabolites and the cytokines (TNF-α, IL-6), hsCRP, and BDNF in the schizophrenia group and the healthy control group." (PMID 34393855, 2021). "Drug-naïve first-episode patients with schizophrenia show an inverse relationship between decreased activity of the enzyme PON1 and increased cytokine levels, including IL-6, IL-4, and IL-10." (PMID 33315097, 2021). "Similar associations have been reported in patients with established schizophrenia for TNF-α and IL-6, in patients with first episode psychosis for IFN-γ and more recently in individuals at ultra-high risk of psychosis with TNF-α and IL-6." (PMID 33667853, 2021). "Significantly elevated levels of macrophage-derived cytokines IL-1β, IL-6, and TNF-α, as well as the Th1-derived cytokine IFN-γ support the macrophage-T-lymphocyte theory of schizophrenia pathophysiology." (PMID 34199832, 2021). "Proinflammatory cytokines, including interleukin-1β (IL-1β), IL-6, and tumor necrosis factor-α (TNF-α), are thought to contribute to the pathogenesis of psychiatric symptoms in schizophrenia by Kyn pathway activation." (PMID 34393855, 2021). "There was a significant increase in the levels of TNFα, IL-1β, and IL-6 and a decrease in the levels of IFN-γ in patients with schizophrenia." (PMID 33552387, 2021).
schizophrenia (continued). "IL-6 decreased following treatment in schizophrenia patients and for MDD patients we observed a trend of decreased IL-6 following treatment." (PMID 33653423, 2021). "Significantly higher plasma levels of IL-6, IL-10, and TNF-α were, however, detected in schizophrenia patients treated with olanzapine or clozapine, as compared with normal controls." (PMID 33746786, 2021). "Duration of illness positively correlated with IL6, IL6R and SERPINA3 mRNAs and negatively correlated with P2RY12 mRNA in schizophrenia." (PMID 34911938, 2021). "Of note, the situation with high IL-6 and low TNF-α observed in ADHD youth in our study has also been observed in patients with Schizophrenia during both exacerbation and remission." (PMID 34413283, 2021). "Findings from the current meta-analysis seem to support elevated levels of pro-inflammatory marker cytokines, such as interleukin-6 (IL-6), IL-1β, and tumor necrosis factor A (TNF-A), in the blood and cerebrospinal fluid of patients with schizophrenia." (PMID 33315097, 2021). "We found marked diagnostic increases in the transcripts of pro-inflammatory cytokines (IL6 and IL1β) and in an acute-phase protein (SERPINA3) in the schizophrenia midbrain." (PMID 31168068, 2021). "It has previously been demonstrated that patients with schizophrenia have lower serum BDNF, MBP, and GFAP levels, but higher serum IL-6 and S100B." (PMID 34025476, 2021). "The data shown in depicted that cytokines including IL-2, IL-6, and TNF-α play a considerable role in the development of schizophrenia." (PMID 33995058, 2021). "Negative correlations were found between the PANSS-T scores and serum levels of IL-6 and between the PANSS-G scores and serum levels of BDNF in the schizophrenia group." (PMID 34393855, 2021). "We also evaluated the serum levels of cytokines (TNF-α, IL-6), hsCRP, and BDNF in patients with schizophrenia and healthy controls." (PMID 34393855, 2021). "Schizophrenia patients have been shown to have high levels of inflammatory cytokines, such as TNF-α, IL-1β, and IL-6, as well as high microglial activation throughout the brain as shown by PET scans and postmortem biopsies." (PMID 33854417, 2021). "To this end, we focused on a panel of plasma cytokines (IL-1β, IL-6, IL-10, TNF-α, and IFN-γ), which have been used previously to assess signs of peripheral inflammation in major psychiatric disorders such as schizophrenia and animal models of MIA." (PMID 33230204, 2021). "Interleukin (IL)-6 levels decreased in schizophrenia (g: −0.48; CI −0.85 to −0.11; p = 0.011), and for MDD a trend of decreased IL-6 levels was observed (g: −0.39; CI −0.87 to 0.09; p = 0.115)." (PMID 33653423, 2021). "There were also moderately strong, significant correlations of KATI mRNA with IL-6 and SERPINA3 mRNAs in people with schizophrenia in the SMRI cohort." (PMID 30940904, 2020). "In the TRC cohort, there were moderately strong, positive, significant correlations between KAT I/II mRNAs and many cytokines assessed (IL-1β, IL-6, and IL-8) and SERPINA3 in schizophrenia and control groups." (PMID 30940904, 2020). "Our results identified the IL-6 × SIRT1 (β = −0.463, t = 10.040, P = 0.002) as the influencing factor for the MetS in schizophrenia patients." (PMID 33324265, 2020). "Regarding studies with only CSF samples, correlations between IL-8 and QUIN, TNF-α and QUIN, and IL-6 and KYNA production were also found in schizophrenia." (PMID 32061259, 2020). "Another study by Schwieler and collaborators detected a significant correlation between IL-6 and KYNA-production in patients with schizophrenia reflected by the tryptophan to KYNA ratio (r = − 0.49; p = 0.024)." (PMID 32061259, 2020). "The results of the present systematic review revealed the following cytokines as possible candidates for deregulatory mechanisms on the kynurenine pathway in schizophrenia: TNF-α, IFN-γ, IL-6, IL-4, IL-8, and IFN-α." (PMID 32061259, 2020).
schizophrenia (continued). "In all patients with schizophrenia, our results showed that plasma levels of SIRT1 were negatively correlated with IL-6 (r = −0.345, P = 0.011), IL-10 (r = −0.276, P = 0.043), and TNF-α (r = −0.393, P = 0.003)." (PMID 33324265, 2020). "In conclusion, the present systematic review found a relationship of elevated IL-6, IL-8, and TNF-α concentrations with the kynurenine pathway in schizophrenia." (PMID 32061259, 2020). "We determined the plasma levels of six cytokines (IL-1β, IL-4, IL-6, IL-10, IL-12 and TNF-α) in schizophrenia patients and healthy controls." (PMID 32038109, 2020). "A meta-analysis reported that pro-inflammatory cytokines, including interleukin (IL)-1β, IL-6, and tumor necrosis factor (TNF)-ɑ, were elevated in the peripheral blood of schizophrenia patients." (PMID 32341334, 2020). "Rats exposed to the cytokine interleukin-6 (IL-6) in utero display deficits in PPI, LI, and social interaction, all deficits commonly observed in rodent models of ASD or schizophrenia." (PMID 30650619, 2019). "The pro-inflammatory cytokines IL-1β, IL-6, and IFN-γ were increased in first-episode schizophrenia compared with controls, similar to previous findings described in meta-analytic studies." (PMID 29803226, 2018). "Future studies will need to determine the relationship between peripheral cytokine levels and expression levels of IL-6, IL-8, and to some extent IL-1β, which have been shown to be elevated in the DLPFC in postmortem tissue from patients with schizophrenia." (PMID 29803226, 2018). "Plasma levels of interleukin (IL)-1β, IL-2, IL-6, and interferon (IFN)-γ were elevated in schizophrenia patients compared to those in controls." (PMID 29803226, 2018). "IL-1β, IL-6, and transforming growth factor-β (TGF-β) are schizophrenia state markers, as they increase in acute relapses and first episode psychosis and normalize with antipsychotic treatment." (PMID 29544672, 2018). "For IL-1β, IL-6 and TNF-α, we observed a significantly higher response in schizophrenia patients than in control subjects (p < 0.05)." (PMID 28646138, 2017). "We have also shown higher levels of three pro-inflammatory cytokines IL-6, IL-8 and TNF-α in the serum of people with schizophrenia, indicating a role of moderate chronic inflammation in schizophrenia." (PMID 28923068, 2017). "Positive correlation between IL-6 plasma levels and the positive symptoms severity were suggested in subjects with ARMS and war veterans with schizophrenia." (PMID 29163240, 2017). "In recent years, neuroinflammatory responses, such as increases in proinflammatory mediators interleukin-6 (IL-6) and tumour necrosis factor-α (TNF-α), have been demonstrated to be involved in the pathology of schizophrenia." (PMID 28373983, 2017). "The same study suggested IL-1β, IL-6 and TGF-β as schizophrenia state markers, since they were elevated in both the first episode and the relapse of the disease, but these markers were decreased after antipsychotic treatment." (PMID 28358316, 2017). "In the case of TLR4 stimulation, there were significantly weaker IL-1β, IL-6, and TNF-α responses in schizophrenia relative to the control subjects (p < 0.01), whereas IL-10 production was intact (p > 0.5)." (PMID 28646138, 2017). "In this study, we examined IL-6 mRNA levels by real-time RT-PCR from fresh extracted peripheral blood mononuclear cells (PBMC) in normal controls and participants with schizophrenia." (PMID 27206977, 2016). "The study also provides significant evidence for strong epistatic interactions among pro-inflammatory cytokine genes IL6 and IFNG in the development of schizophrenia." (PMID 27177030, 2016). "The volumes of cortical grey matter and SFG were significantly negatively correlated with IL-6 and SERPINA3 mRNAs for both the whole cohort and the schizophrenia group only (all −0.700<r<−0.341, P<0.01)." (PMID 27959331, 2016).